PPARA (peroxisome proliferator activated receptor alpha)
Description:
Ligand-activated transcription factor. Key regulator of lipid metabolism. Activated by the endogenous ligand 1-palmitoyl-2-oleoyl-sn-glycerol-3-phosphocholine (16:0/18:1-GPC). Activated by oleylethanolamide, a naturally occurring lipid that regulates satiety. Receptor for peroxisome proliferators such as hypolipidemic drugs and fatty acids. Regulates the peroxisomal beta-oxidation pathway of fatty acids. Functions as a transcription activator for the ACOX1 and P450 genes. Transactivation activity requires heterodimerization with RXRA and is antagonized by NR2C2. May be required for the propagation of clock information to metabolic pathways regulated by PER2.
Synonyms: PPAR-alpha; NR1C1; PPAR; hPPAR; PPARalpha
Tractability: Small molecule: an approved drug acts on it; a structure with a bound ligand is known; a high-quality ligand is known; it has a high-quality binding pocket; it belongs to a druggable protein family. PROTAC: UniProt records ubiquitination sites on it; a small molecule that binds it is known.
Target class: Nuclear receptor; Transcription factor; Nuclear hormone receptor subfamily 1; Nuclear hormone receptor subfamily 1 group C; Nuclear hormone receptor subfamily 1 group C member 1
Chemical probes: GW7647 (high quality), NXT629
Safety:
Unwanted effects reported when the protein is acted on. In parentheses: how it was acted on, where the effect was seen, and who reports it.
Increased, Liver Steatosis (AOP-Wiki: activation, liver; AOP-Wiki; AOP-Wiki: inhibition)
impaired, Fertility (activation; liver; source: AOP-Wiki)
Decrease, Population growth rate (activation; liver; source: AOP-Wiki)
Decreased, Body Weight (inhibition; source: AOP-Wiki)
Increased, Pancreatic acinar tumors (activation; source: AOP-Wiki)
Malformation, Male reproductive tract (activation; liver; source: AOP-Wiki)
Viable offspring, decreased (activation; liver; source: AOP-Wiki)
new-onset diabetes after transplantation (source: ClinPGx)
Gene: Protein-coding gene on chromosome 22 (46,149,924 to 46,243,755, forward strand). Ensembl gene ENSG00000186951.
Subcellular location: Nucleus
Subcellular location (Human Protein Atlas): Primary cilium; Basal body; Centriolar satellite; Nuclear bodies; Nucleoli fibrillar center
Pathways (Reactome):
Circadian clock: BMAL1:CLOCK,NPAS2 activates circadian expression; Expression of BMAL (ARNTL), CLOCK, and NPAS2; RORA,B,C and NR1D1 (REV-ERBA) regulate gene expression
Metabolism: Activation of gene expression by SREBF (SREBP); PPARA activates gene expression; Regulation of lipid metabolism by PPARalpha
Cellular responses to stimuli: Cytoprotection by HMOX1; Heme signaling
Developmental Biology: Transcriptional regulation of brown and beige adipocyte differentiation by EBF2; Transcriptional regulation of white adipocyte differentiation
Gene expression (Transcription): Nuclear Receptor transcription pathway
Metabolism of proteins: SUMOylation of intracellular receptors
Organelle biogenesis and maintenance: Transcriptional activation of mitochondrial biogenesis
Gene Ontology:
Molecular function: DNA-binding transcription activator activity; DNA-binding transcription activator activity, RNA polymerase II-specific; DNA-binding transcription factor activity; DNA-binding transcription repressor activity, RNA polymerase II-specific; lipid binding; nuclear receptor activity; nuclear steroid receptor activity; protein binding; RNA polymerase II cis-regulatory region sequence-specific DNA binding; RNA polymerase II-specific DNA-binding transcription factor binding; ubiquitin conjugating enzyme binding; DNA binding; DNA-binding transcription factor activity, RNA polymerase II-specific; sequence-specific DNA binding; DNA-binding transcription factor binding; MDM2/MDM4 family protein binding; mitogen-activated protein kinase kinase kinase binding; NFAT protein binding; phosphatase binding; protein domain specific binding; protein-containing complex binding; signaling receptor activity; transcription coactivator binding; zinc ion binding
Biological process: defense response to virus; negative regulation of cholesterol storage; negative regulation of cytokine production involved in inflammatory response; negative regulation of glycolytic process; negative regulation of hepatocyte apoptotic process; negative regulation of inflammatory response; negative regulation of leukocyte cell-cell adhesion; negative regulation of macrophage derived foam cell differentiation; negative regulation of miRNA transcription; negative regulation of phosphatidylinositol 3-kinase/protein kinase B signal transduction; negative regulation of reactive oxygen species biosynthetic process; negative regulation of transcription by RNA polymerase II; negative regulation of transforming growth factor beta receptor signaling pathway; peroxisome proliferator activated receptor signaling pathway; positive regulation of ATP biosynthetic process; positive regulation of DNA-templated transcription; positive regulation of lipid biosynthetic process; positive regulation of transcription by RNA polymerase II; regulation of fatty acid metabolic process; regulation of ketone metabolic process; cell differentiation; cellular response to starvation; circadian regulation of gene expression; fatty acid metabolic process; hormone-mediated signaling pathway; and 21 more
Cellular component: fibrillar center; nuclear body; nucleus; chromatin; nucleoplasm; RNA polymerase II transcription regulator complex
Genetic constraint (gnomAD): Loss-of-function variants: 22 observed, 44.17 expected, observed/expected ratio (o/e) 0.5, 90% interval 0.35 to 0.71. The upper end of that interval is the gene's LOEUF score, 0.71, which puts it in group 2 of 6, group 1 being the genes least tolerant of losing a copy. Missense variants: 465 observed, 640.37 expected, observed/expected ratio (o/e) 0.73, 90% interval 0.67 to 0.78. Synonymous variants: 242 observed, 254.32 expected, observed/expected ratio (o/e) 0.95, 90% interval 0.86 to 1.06.
Homologues: Orthologues: macaque PPARA (99% identical), chimpanzee PPARA (99% identical), dog PPARA (95% identical), pig PPARA (94% identical), mouse Ppara (92% identical), rabbit PPARA (92% identical), rat Ppara (92% identical), guinea pig PPARA (89% identical), tropical clawed frog ppara (82% identical), zebrafish pparab (72% identical), zebrafish pparaa (66% identical), Caenorhabditis elegans sex-1 (26% identical), and 184 more. Paralogues in human: PPARD (60% identical), PPARG (56% identical), NR1D2 (29% identical), NR1D1 (28% identical), RARG (27% identical), RARB (26% identical), RARA (25% identical), RORA (24% identical), RORC (23% identical), THRB (23% identical), RORB (23% identical), NR1H4 (22% identical), and 6 more.
Diseases named in the same sentence as PPARA in open-access papers:
PPARA is named in the same sentence as 614 diseases in open-access papers, as found by Europe PMC text mining. Sharing a sentence is not in itself a finding about the gene and the disease. The quoted sentences say what the papers report.
Obesity (673 papers, 2005 to 2026). Accumulation of substantial excess body fat. "These key molecular initiating events with PPARα activation are central to the disruption of most pathways associated with obesity, diabetes, high cholesterol, and other metabolic-dysfunction-associated fatty liver diseases (MAFLDs)." (PMID 41012353, 2025). "A number of prevalent metabolic disorders such as obesity, atherosclerosis and type 2 diabetes mellitus are associated with a shift in this balance, so PPARα and PPARγ in particular, are of interest pharmacologically." (PMID 39040675, 2024). "Abnormal alteration of PPARα is associated with the pathogenesis of many diseases, such as obesity, cardiovascular diseases, diabetes, and inflammation." (PMID 38291059, 2024). "Studies in mice have revealed the importance of PPARα in attenuating obesity caused by high-fat diets." (PMID 37899888, 2023). "These metabolic outcomes emerge from the mitigation of fatty acid oxidation, mediated by the obesity-associated gene and peroxisome proliferator-activated receptor alpha (PPARα)." (PMID 37874430, 2023). "We herein demonstrate that monomeric CtBP2, the predominant form in the metabolic milieu associated with obesity, represses the transcriptional activity of PPARα." (PMID 37286039, 2023). "PPARα-deficient ob/ob mice develop more severe obesity and hepatic steatosis compared to ob/ob mice." (PMID 36172518, 2022). "This suggests that obesity-associated Fabp1 upregulation is promoted by fatty acids via the PPARα and TBK1–IKKε–IRF3 pathways." (PMID 36400935, 2022). "Knockout of PPARα in mice causes a high miscarriage rate, hepatic lipid accumulation, obesity, and prolonged inflammation." (PMID 36359869, 2022). "CPT1, as a target gene of PPARα, is an essential enzyme in fatty acid ß-oxidation and is associated with hyperlipemia and obesity." (PMID 35990329, 2022). "The present study reports the molecular mechanisms underlying the anti-obesity and glucose-lowering effects of VS extract by regulating C/EBPα-mediated lipogenesis, PPARα-mediated fatty acid β-oxidation, and PPARγ-mediated insulin sensitivity." (PMID 33671428, 2021). "Consistently, we found that the aberrant demethylation of Pparα was associated with lipid metabolism disorders and obesity in offspring." (PMID 33955677, 2021). "In obesity, PPARα/δ target genes are highly upregulated, thus causing inhibition of IFN-γ production as well as the downstream transcription of other cytotoxic granules in adipose tissue NK cells." (PMID 34212054, 2021). "Macrophages are important regulators of obesity-associated inflammation and PPARα and -γ agonism in macrophages has anti-inflammatory effects." (PMID 31903139, 2020). "In the present study, we evaluated the importance of hepatocyte PPARα in steatosis associated with diet-induced obesity." (PMID 32300166, 2020). "PPARα-deficient ob/ob mice with obesity-related insulin resistance develop pancreatic β-cell dysfunction characterized by reduced mean islet surface area and decreased insulin secretion in response to high glucose." (PMID 32708786, 2020). "Alterations of PPARα expression or activity were associated with various diseases such as obesity and NAFLD." (PMID 33224240, 2020). "The genes altered in the lower PUFA:SFA ratio were associated with adipogenesis, gene regulation by PPARα, regulation of energy intake, the inflammatory process and obesity." (PMID 31615571, 2019). "Tesaglitazar is part of a larger family of PPARα/γ dual agonists, which effectively improve insulin sensitivity and dyslipidemia in patients with diabetes and obesity-associated dysmetabolism." (PMID 31725756, 2019). "In a diet-induced obesity model, the PPARα agonist fenofibrate, elicits weight loss and increases β3-AR, PGC-1α and UCP-1 in brown adipocytes." (PMID 31346342, 2019). "High-fat diet-induced hepatic steatosis in obesity was associated with decreased AMPKα activity and disturbed PPARα and SREBP-1c related lipid metabolism signaling pathway." (PMID 30398974, 2018).
Obesity (continued). "Although the association between genetic variants of the PPARG gene and obesity traits has been widely studied, as far as we know there is limited evidence regarding the relationship between PPARA variants and obesity phenotype." (PMID 29795275, 2018). "Increasing evidence suggests that PPARα plays a main role in the management of obesity, especially central obesity associated with IR syndromes, given its involvement in the regulation of lipid metabolism and inflammation." (PMID 30428868, 2018). "Cevoglitazar, a dual agonist of PPARα/γ, is currently being developed for the treatment of dyslipidemia and obesity associated with T2DM." (PMID 30060458, 2018). "Last, we found that the retinoblastoma protein RB1, which also participates in the PPARA pathway, is associated with insulin resistance, obesity, and metabolic disturbances in mice." (PMID 28549478, 2017). "There is a demand for safe and potent anti-obesity drugs, because currently available anti-obesity drugs, such asorlistat (gastrointestinal lipase inhibitor) and fibrates (PPARα agonists), cause undesirable side effects." (PMID 27398599, 2016). "Our studies highlight the association (in terms of timing and tissue-specificity) of obesity-related clock gene disruption with altered PPARα and PPARγ expression and local tissue inflammation." (PMID 27439882, 2016). "There are three types of PPARs, PPARα, PPARβ and PPARƳ among which variations in PPARƳ gene are mostly implicated in obesity, diabetes and many other disorders." (PMID 27625707, 2016). "Pparα has been implicated in obesity and metabolic diseases while Pgc1α plays an important role in the crosstalk between circadian clock circuitry and metabolism." (PMID 25837425, 2015). "Although both control and the advanced group of rats were fasted for 8–10h before sacrifice, the advanced group showed a decrease in liver Fgf21 and Pparα suggesting a predisposition to obesity." (PMID 25837425, 2015). "A case-control study of NAFLD patients highlighted a potentially protective role for the Val227Ala variant of PPARα against obesity compared to subjects with the wild-type receptor." (PMID 23346097, 2013). "Asin the case of Rap1 deficiency, PPARα abrogation leads to amore pronounced obesity phenotype in females than in males, although males alsodevelop hepatic steatosis." (PMID 23791526, 2013). "Inparticular, similar to Rap1 deficiency, PPARα deficiencyleads to a late onset of spontaneous obesity with a remarkable sexual dimorphism." (PMID 23791526, 2013). "A number of polymorphisms have been described in the association of the PPARα and PPARγ isoforms with obesity." (PMID 23545576, 2013). "Activation of hypothalamic PPARα and/or PPARγ has been implicated in weight gain and obesity, potentially consistent with elevated adiposity and DIO in PPARδ KO mice." (PMID 22916190, 2012). "Studies in mice have shown that PPARα-deficient animals were unable to metabolize lipids and develop late onset obesity even when kept on a stable diet." (PMID 17705849, 2007). "PPARA scored highly in the Bayesian analysis as a gene linked to obesity." (PMID 39796277, 2025). "By encouraging the use of fatty acids as an energy source, PPARα activation can lessen the build-up of fat in tissues and may help regulate metabolic problems linked to obesity." (PMID 40066031, 2025). "The inhibition of the PPARA gene could improve lipid profiles by enhancing fatty acid oxidation, and its dysfunction may cause obesity and insulin resistance." (PMID 40723896, 2025). "RCTs specifically designed to evaluate HF outcomes are essential to clarify whether PPARα agonists can complement established neurohormonal treatments, particularly in the context of the rising burden of HFpEF associated with obesity and type 2 diabetes." (PMID 41007642, 2025).
Obesity (continued). "Furthermore, PPARα-deficient mice suffered from obesity, and their livers showed steatosis, inflammation, oxidative stress, and apoptosis." (PMID 36615764, 2022). "Using PPARα-deficient mice fed a high-fat diet, PPARα has been shown to protect against obesity-induced liver inflammation via the downregulation of inflammatory genes and the attenuation of adipose-tissue inflammation, partially through the prevention of fat accumulation in the liver." (PMID 35954274, 2022). "Similarly, studies conducted in animal models reported that increased PPARα promoter methylation was associated with decreased PPARα expression, insulin resistance and hyperlipidemia and obesity in offspring exposed to unhealthy diets during gestation." (PMID 36992770, 2022). "Many PPARα target genes are involved in fatty acid metabolism, particularly hepatic fatty acid and plasma lipoprotein metabolism, which are intimated associated with obesity and dyslipidemia." (PMID 36234935, 2022). "We speculated that the DNA demethylation level of Pparα associated with lipid metabolism disorders and obesity in offspring." (PMID 33955677, 2021). "Finally, reduced PPARα expression increased the risk of obesity in offspring from mothers given a HFD." (PMID 33955677, 2021). "Research on mice showed that PPARα modulated the methylation of liver Fgf21 and represents a form of epigenetic memory that persists from the postnatal period into adulthood that influence the risk of obesity in later life." (PMID 33670024, 2021). "In the current study, HBO treatment may alleviate HFD-induced fatty acid metabolism dysfunction/obesity in C57/B6 mice, which seems to be associated with corrected circulation and skeletal muscle L-carnitine levels and PPARα expression levels." (PMID 31906305, 2020). "However, whole body Pparα deficiency has a stronger influence on the effect of HFD-induced obesity on liver metabolic homeostasis." (PMID 32300166, 2020). "Melatonin may alleviate insulin resistance and obesity caused by persistent artificial light exposure in guinea pigs, likely via activation of the AMPKα/PPARα signaling pathway." (PMID 33150187, 2020). "Many studies have reported that they played a crucial role in the prevention and treatment of obesity-associated insulin resistance, and might via the upregulation of PPARα target genes, thereby increasing fatty acid oxidation." (PMID 32467715, 2020). "PPARa also has an important role in energy metabolism, and its deficiency causes obesity in rats." (PMID 31835772, 2019). "Due to the importance of the polymorphic forms analyzed in PPARA gene in the etiology of many human diseases, they can be used as a molecular tool of pro-health prophylaxis, helpful in estimating the risk of disorders, such as obesity." (PMID 31319591, 2019). "It has been found that the activation of PPARα and PPARγ attenuates total free fatty acid and triglyceride accumulation, which may reduce the risk of obesity, diabetes, and atherosclerosis." (PMID 31010169, 2019). "In addition to its role in fatty acid metabolism, PPARa is also associated with conditions such as obesity and diabetes, as well as various cardiovascular conditions including hypertension and atherosclerosis." (PMID 31737045, 2019). "Another area of PPAR research that deserves further exploration, not counting global knockout studies and systemic agonist treatment, is the specific role of PPARα in immune cells in the context of atherosclerosis and obesity-associated inflammation and insulin resistance." (PMID 29799467, 2018). "PPARA is a susceptibility gene for obesity, T2DM and insulin resistance." (PMID 27337171, 2016). "Consistently, it was shown that PPARα functions on obesity could be enhanced in estrogen-deficient states e.g. ovariectomized females." (PMID 25909471, 2015). "Because PPARα is associated with obesity, insulin resistance, and type 2 diabetes, this receptor may also influence sleep quality." (PMID 23383010, 2013).